PLCB1 (phospholipase C beta 1)
Diseases named in the same sentence as PLCB1 in open-access papers (continued):
Sharing a sentence is not in itself a finding about the gene and the disease.
tumor (27 papers, 2011 to 2025). "We verified the involvement of T-cell receptor signaling pathways in HNSCC as well as associated oncogenes such as LCK and PLCB1, and tumor suppressors such as STAT5A, PTPN6, PARK2." (PMID 21884569, 2011). "The GSEA revealed that the genes correlated with PLCB1, including HEY1, EZH2, VEGFA, E2F3, and STC1, were enriched in angiogenesis, suggesting that the increased expression of PLCB1 might be associated with HCC recurrence via tumor-associated angiogenesis." (PMID 35707353, 2022). "We found that PLCB1 was correlated with the degree of tumor differentiation and tumor metastasis by analyzing the expression level of PLCB1 in NSCLC patients." (PMID 38778543, 2024). "By reviewing the relevant literature, we found that PLCB1 is significantly important in the regulation of various tumor cells." (PMID 38778543, 2024). "Overall, the fucose residue in GHCer dictated the glycan conformation for its complexing with TRAX to release TRAX-sequestered PLCβ1, leading to Ca2+ mobilization in endothelial cells and enhancing angiogenesis in tumor microenvironments." (PMID 36517806, 2022). "The results demonstrate that the expression of EGFR, IGF1, PTGS2, FGF1, CAV1, and PLCB1 were significantly different (p < 0.01) in PABC tissues as compared to non-tumor tissues, with a similar pattern to that observed in the microarray analysis." (PMID 36035177, 2022). "Since the competitiveness between GHCer and PLCβ1 is dose-dependent, it would be of interest to ascertain the concentration of GHCer in the conditioned medium of tumor cells." (PMID 36517806, 2022). "In conclusion, Lnc1 promoted tumor proliferation and migration mediated by PLCB1." (PMID 38778543, 2024). "In addition, PLCB1 is related to tumor differentiation and metastasis by analyzing the expression level of PLCB1 in clinical specimens." (PMID 38778543, 2024). "The results showed that PLCB1 expressed at a high level in the tumor tissues." (PMID 38778543, 2024). "Next, to investigate whether Lnc1 regulated the proliferate and metastatic ability of tumor cells in a PLCB1‐mediated manner." (PMID 38778543, 2024). "Finally, both synthetic GHCer and the GHCer from tumor-secreted extracellular vesicles (EVs) were validated to compete with PLCβ1 for complexing with TRAX and induce angiogenesis in vitro and in vivo." (PMID 36517806, 2022). "As an important member of the phospholipase family, PLCB1 plays an important role in intracellular signal transduction, and abnormal signal transduction is often one of the important reasons for disease progression and tumor progression." (PMID 36611865, 2022). "As a result, we found that ITPR1, ITPR2, and ITPR3 proteins may interact with tumor-promoting genes, such as PLCB1, PLCB2, PRKCA, and RGS21, which may partially explain its oncogene roles." (PMID 35580861, 2022). "Interestingly, in both tumor and normal astrocyte models silenced for PLCβ1, it was observed an increased expression of Slug, an essential transcriptional factor that is involved in the regulation of mesenchymal phenotype, and N-Cadherin, one of the main mesenchymal markers." (PMID 35303162, 2022). "Sun and colleagues first established the ENO1-YAP1/PLCB1/HPGD regulatory axis, demonstrating its glycolytic-independent mechanism in promoting tumor growth via arachidonic acid (AA) metabolic reprogramming." (PMID 41353343, 2025). "Two sets of genes were chosen, PDGFRA, Lin28A, THBS1, JUN, PLCB1 and GABRA5, which were found to be up- and down-regulated, respectively, in support of tumour cell proliferation." (PMID 38000389, 2024). "There are numerous reports linking changes in the mRNA expression of PLCB1 in NSCLC cell lines and/or tumor tissues." (PMID 31080817, 2019). "Moreover, we showed that, following the silencing of PLCβ1, there is a consequent increment in ERK1/2 pathway activation, that is a fundamental pro-surviving factor involved in tumor progression and resistance to current therapies." (PMID 35303162, 2022).
tumor (continued). "Similarly, ITGB3 and PLCB1 were also confirmed to facilitate HCC progression by enhancing the adhesion and proliferation of tumor cells." (PMID 31761783, 2019). "In this study, we demonstrated the competition with PLCβ1 for binding to TRAX by either GHCer, or tumor-secreted EVs containing GHCer, resulting in the release of the TRAX-sequestered PLCβ1, leading to Ca2+ mobilization in endothelial cells and enhanced angiogenesis in tumor microenvironment." (PMID 36517806, 2022). "However, the extent to which each cell type contributes to the overall level of PLCβ1 detected in patient tumor tissue has not been well studied." (PMID 26614510, 2016). "Although the genes in (PRKAA2, GNG7, MYL3, NOS1, ADCY1, PLCB1, MYLK3, and MYLK4) the apelin/APJ signaling axis are found to be downregulated and might not be considered responsible in cdRCC progression, downregulation of GNG7 tells a different story due to its tumor‐suppressive activity." (PMID 40304310, 2025). "Furthermore, we measured the MVD in tumor tissues from the nude mice, and found that the KD group had significantly lower MVD than the controls (CON group) (t test, P-value < 0.05), indicating that PLCB1 silencing could decrease the MVD in HCC." (PMID 35707353, 2022). "The analysis of the corresponding tumor and non-tumor samples also revealed upregulation of COMP, matrix proteins such as COL5A1, COL11A1, and FN1, and genes of the Wnt pathway (WNT7B, FZD10, SFRP2), while PLCB1, CAMK2B, PLCB4 and WIF1 are downregulated." (PMID 33227073, 2020).
psychiatric disorder (3 papers, 2011 to 2024). A disorder characterized by behavioral and/or psychological abnormalities, often accompanied by physical symptoms. "Going forward, further studies on the association of PLCβ1 with PTSD might provide notable insights into the susceptibility to this psychiatric disease." (PMID 38959322, 2024).
benign tumor (2 papers, 2021 to 2024). "Moreover, we selected 10 pairs of patients, pathologically diagnosed as NSCLC and benign tumor in clinical, to analyze the PLCB1 expression by RT‐qPCR." (PMID 38778543, 2024).
hematologic malignancies (2 papers, 2016 to 2022). "Evidence exists that PLCβ1 interconnected with PI3K/AKT/mTOR signaling in solid tumors and hematological malignancies." (PMID 26614510, 2016).
adenocarcinoma (1 paper, 2019). A common cancer characterized by the presence of malignant glandular cells. "High mRNA expression levels of PLCB1, PLCB2, and PLCB3 were significantly associated with poor overall survival (OS) of all NSCLC patients and significantly associated with poor prognosis of adenocarcinoma." (PMID 31080817, 2019).
inflammation (1 paper, 2016). Aberrant reaction of the microcirculation characterized by movement of fluid and leukocytes from the blood into extravascular tissues. "Altogether, these data suggest the involvement of DHHC21-mediated PLCβ1 palmitoylation in endothelial inflammation." (PMID 27653213, 2016).
PLCB1 also shares sentences with these, for which no sentence is quoted: neurological diseases (4 papers); brain disorder (3); cholangiocarcinoma (3); Cognitive impairment (3); Kawasaki disease (3); acute myeloid leukemia (2); Alzheimer disease (2); atherosclerosis (2); cardiovascular diseases (2); Huntington disease (2); neurodevelopmental disorder (2); non-small cell lung carcinoma (2); ovarian carcinoma (2); West Syndrome (2); abdominal aortic aneurysm (1); amyotrophic lateral sclerosis (1); blood disease (1); cervical carcinoma (1); coloboma (1); congenital megacolon (1); Crohn disease (1); dementia (1); developmental delay (1); diabetic cardiomyopathies (1); head and neck tumours (1); infection (1); inflammatory bowel disease (1); Joubert syndrome (1); liver cancer (1); lung fibrosis (1).
A further 20 diseases each share a sentence with PLCB1 in 1 paper.